STUB1 (STIP1 homology and U-box containing protein 1)
Diseases named in the same sentence as STUB1 in open-access papers (continued):
Sharing a sentence is not in itself a finding about the gene and the disease.
osteoporosis (4 papers, 2015 to 2025). A condition of reduced bone mass, with decreased cortical thickness and a decrease in the number and size of the trabeculae of cancellous bone (but normal chemical composition), resulting in increased fracture incidence. "Among the E3 ligases, the carboxyl terminus of the Hsp70-interacting protein (CHIP or STUB1) and Itch have received much attention due to their role in TRAF regulation of osteoporosis." (PMID 40496246, 2025).
osteosarcoma (4 papers, 2018 to 2023). A usually aggressive malignant bone-forming mesenchymal neoplasm, predominantly affecting adolescents and young adults. "Moreover, high protein level of STUB1 was associated with better overall survival in osteosarcoma patients." (PMID 36529692, 2023). "Using the orthotopic osteosarcoma lung metastasis model with 143B‐luc cells in vivo, we determined that knockdown of STUB1 by shRNA increased and overexpression of STUB1 reduced lung metastasis, respectively." (PMID 36529692, 2023). "Taken together, our results illustrate that STUB1 acts as a tumor suppressor in osteosarcoma." (PMID 36529692, 2023). "Because STUB1's function in osteosarcoma has not yet been determined, we sought to do so." (PMID 36529692, 2023).
breast tumors (3 papers, 2012 to 2022). "Deletion of STUB1 in human prostate and breast tumour cells further sensitized them to growth inhibition induced by IFNγ." (PMID 35982220, 2022). "STUB1 is overexpressed in thyroid, kidney, prostate, and breast tumours compared to their adjacent normal tissues, while a reverse trend is found in gastric cancer." (PMID 35982220, 2022).
Cerebral ischemia (3 papers, 2018 to 2024). Restriction of arterial blood supply to the brain associated with insufficient oxygenation to support the metabolic requirements of the tissue. "rAAV8-733-mediated gene transfer of CHIP/Stub-1 reduces the expression of ubiquitinated proteins, which contributes to the prevention of hippocampal neuronal death in an animal model of brain ischemia." (PMID 32089771, 2020).
dementia (3 papers, 2020 to 2023). Loss of intellectual abilities interfering with an individual's social and occupational functions. "Within the context of dementia pathogenesis, we want to outline the case of severe early-onset dementia resembling frontotemporal dementia associated with a specific intronic splice donor variant in the STUB1 gene." (PMID 38132139, 2023). "Mutations in STUB1 cause autosomal recessive spinocerebellar ataxia type 16 (SCAR16) with widespread neurodegeneration manifesting as spastic-ataxic gait disorder, dementia and epilepsy." (PMID 33097556, 2020).
Gordon Holmes syndrome (3 papers, 2017 to 2021). "CHIP is encoded by STIP1 homology and U-box containing gene 1 (STUB1) in humans, and their mutations are associated with multiple pathological disorders, including the Gordon Holmes syndrome, brain diseases (e.g., intracranial aneurysm), and lung inflammation." (PMID 34305988, 2021). "It adds further support of STUB1 as one important cause of Gordon Holmes syndrome, which shows a substantial genetic heterogeneity as it can also be caused by mutations in e.g. PNPLA6." (PMID 28193273, 2017).
liver cancer (3 papers, 2021 to 2025). An epithelial or non-epithelial malignant neoplasm that arises from the liver. "For example, the E3 ubiquitin ligase STUB1 mediated ubiquitination can reduce the stability of VEZF1 and attenuate liver cancer progression." (PMID 40858565, 2025). "VEZF1 transcriptionally activates progestin and adipoQ receptor 4 (PAQR4) to accelerate HCC progression, while STUB1-mediated ubiquitination of VEZF1 leads to diminished transcriptional activity and attenuated liver cancer development." (PMID 40858565, 2025). "Growth differentiation factor 15 (GDF15) facilitated tumor immunosuppression via interaction with CD48 on Treg cells and downregulation of E3 ligase STUB1, leading to accumulation of FOXP3 protein in liver cancer." (PMID 36733484, 2023).
steatosis (3 papers, 2016 to 2025). Increased lipid within the cytoplasm of cells. "We propose a novel pathophysiological model of HFpEF in which suppression of the Xbp1s arm of the UPR blunts STUB1 expression, leading to the stabilization and overactivation of FoxO1 in cardiomyocytes with consequent cardiomyocyte steatosis and associated detrimental sequelae." (PMID 33727534, 2021). "Although the relationship between STUB1 and hyperlipidemia has not been confirmed, research has indicated that upregulation of STUB1 may alleviate lipid droplet accumulation and steatosis in the liver of mice, improving non-alcoholic fatty liver disease." (PMID 40245021, 2025).
viral infection (3 papers, 2015 to 2022). "Upon virus infection, nuclear MLL5 protein translocates from the nucleus to the cytoplasm inducing STUB1-mediated degradation of RIG-I." (PMID 29593341, 2018). "STUB1 could interact with SARS-CoV-2 M and ORF3A protein, suggesting that STUB1 may regulate viral infection by catalyzing the ubiquitination of these two viral proteins." (PMID 36071039, 2022). "Moreover, upon viral infection, MLL5 protein translocates from the nucleus to the cytoplasm to induce STUB1-mediated RIG-I degradation." (PMID 29593341, 2018).
autosomal dominant cerebellar ataxia (2 papers, 2020 to 2024). A clinically and genetically heterogeneous group of neurodegenerative diseases characterized by a slowly progressive ataxia of gait, stance and limbs, dysarthria and/or oculomotor disorder, due to cerebellar degeneration in the absence of coexisting diseases. "SCA48, the most recently described autosomal dominant spinocerebellar ataxia due to heterozygous mutations in STUB1 gene." (PMID 39707479, 2024).
Cerebellar atrophy (2 papers, 2014 to 2020). Cerebellar atrophy is defined as a cerebellum with initially normal structures, in a posterior fossa with normal size, which displays enlarged fissures (interfolial spaces) in comparison to the foliae secondary to loss of tissue. "The main findings of our MRI analyses were severe cerebellar atrophy, as reported by previous studies with STUB1 mutations, and in addition a distinct thinning of the anterior part of the corpus callosum (CC), not reported previously." (PMID 25258038, 2014).
cervical cancer (2 papers, 2024 to 2025). A primary or metastatic malignant neoplasm involving the cervix. "We also clarify that BAG2 stabilizes STING by preventing STING from being ubiquitinated by STUB1, thereby preventing cervical cancer proliferation and metastasis." (PMID 40364789, 2025). "BAG2 inhibits the ubiquitination and degradation of STING by forming a complex with STUB1, thereby activating the type I IFN signaling pathway and inhibiting the development of cervical cancer." (PMID 40364789, 2025).
cholangiocarcinoma (2 papers, 2024 to 2025). A carcinoma that arises from the intrahepatic biliary tree (intrahepatic cholangiocarcinoma) or from the junction, or adjacent to the junction, of the right and left hepatic ducts (hilar cholangiocarcinoma). "We evaluated the effects of STUB1/UHRF1 on cholangiocarcinoma by utilizing a primary CCA mouse model." (PMID 39267107, 2024). "STUB1 actively participates in the regulation of PLA2G2A transcription through these PTMs and influences the progression of cholangiocarcinoma." (PMID 39267107, 2024). "Furthermore, pan‐cancer analysis based on the TCGA database revealed a strong negative correlation between METTL14 and STUB1 expression across most cancers, particularly in cholangiocarcinoma (CCA)." (PMID 40919129, 2025).
chronic obstructive pulmonary disease (2 papers, 2017 to 2023). A chronic and progressive lung disorder characterized by the loss of elasticity of the bronchial tree and the air sacs, destruction of the air sacs wall, thickening of the bronchial wall, and mucous accumulation in the bronchial tree. "Interestingly, STUB1 mRNA levels are up-regulated in the airways of subjects with asthmatic and chronic obstructive pulmonary disease (COPD), suggesting that elevation of STUB1 expression may serve as a possible feedback mechanism in an effort to dampen IL-4Rα signaling." (PMID 28721208, 2017).
Dystonia (2 papers, 2025). An abnormally increased muscular tone that causes fixed abnormal postures. "Proband 6 (F6: II-1) presented with an SCA17 subtype characterized by dystonia (torsional spasm) and spastic paraplegia, carrying a TBP gene CAG/CAA repeat expansion of 41 repeats without concurrent STUB1 heterozygous mutations." (PMID 41001200, 2025).
epilepsy (2 papers, 2020 to 2025). A brain disorder characterized by episodes of abnormally increased neuronal discharge resulting in transient episodes of sensory or motor neurological dysfunction, or psychic dysfunction. "Recently, patients with STUB1 ataxia were shown to present a broader neurodegeneration with complex clinical phenotypes of cognitive impairment, epilepsy and hypogonadism in addition to spastic-ataxic movement disorder." (PMID 33097556, 2020). "Of note, many seizure-related genes identified in this study (for e.g. ACBD5, SLC6A5, STUB1) are not included in the routine epilepsy panel (R59) and this highlights the benefit of the gene-agnostic analytic approach offered by the rapid WES testing." (PMID 40399560, 2025).
gout (2 papers, 2022 to 2025). A condition characterized by painful swelling of the joints, which is caused by deposition of urate crystals. "These active ingredients may target protein processing in the endoplasmic reticulum through HSPA1B, HSP90AB1, and STUB1 proteins and play a significant role in treating gout." (PMID 36276864, 2022). "Our PPI analysis showed that turmeric and corn silk influence gout through their impact on a complex biological network, including HSPA1B, HSP90AB1, STUB1, CTNNB1, YWHAG, and YWHAZ." (PMID 36276864, 2022). "We found bisacumol, campesterol, and stigmasterol to be the main turmeric compounds that exerted a marked effect on gout treatment by targeting protein processing in the endoplasmic reticulum through the HSPA1B, HSP90AB1, and STUB1 proteins." (PMID 36276864, 2022). "Candidate targets of turmeric for gout were HSPA8, VCP, HSP90AB1, HSPA5, HSPA1B, NFKB1, and STUB1." (PMID 36276864, 2022).
hypogonadotrophic hypogonadism (2 papers, 2014 to 2017). "Finally, our data provide the first confirmation from an independent family showing that hypogonadotropic hypogonadism is indeed part of the phenotypic cluster of STUB1 mutations." (PMID 28193273, 2017). "This suggests that hypogonadotrophic hypogonadism may not be an obligatory feature of STUB1-related disease." (PMID 25258038, 2014).
pulmonary fibrosis (2 papers, 2021 to 2025). Chronic progressive interstitial lung disorder characterized by the replacement of the lung tissue by connective tissue, leading to progressive dyspnea, respiratory failure, or right heart failure. "Given Azithromycin’s dual function in suppressing autophagy and activating STUB1, it holds potential for therapeutic use in pulmonary fibrosis by targeting NOX4 and Smad3 degradation." (PMID 40901482, 2025). "Azithromycin (AZM) has been found to inhibit autophagy and contribute to the development of pulmonary fibrosis by increasing NOX4 ubiquitination through elevated STUB1 protein levels." (PMID 40901482, 2025). "Because azithromycin inhibits autophagy, which activates STUB1, it may be a potential therapeutic drug for pulmonary fibrosis by promoting degradation of both NOX4 and Smad3." (PMID 34198949, 2021). "STUB1-mediated degradation of NOX4 inhibits myofibroblast differentiation, which results in bleomycin-induced pulmonary fibrosis." (PMID 34198949, 2021). "Consequently, STUB1-mediated degradation of NOX4 inhibits myofibroblast differentiation, playing a key role in reducing bleomycin-induced pulmonary fibrosis." (PMID 40901482, 2025).
alcoholic cirrhosis (1 paper, 2021). "Analyses of RNAseq from patients with alcoholic hepatitis showed increased expression of numerous ERAD genes, including those involved in CYP2E1 turnover (AMFR and VCP), though this reversed in patients with alcoholic cirrhosis, who displayed reduced expression of Stub1/CHIP." (PMID 35174209, 2021).
corticotroph adenoma (1 paper, 2025). "Compared to normal pituitary glands, the expression of STUB1 was found to be downregulated in corticotroph adenomas." (PMID 40859326, 2025). "Then a semi-quantitative immunohistochemical analysis of nuclear-localized STUB1 was performed, demonstrating that STUB1 protein levels were also downregulated in ACTH-secreting corticotroph adenoma compared to SCAs." (PMID 40859326, 2025). "Taken together, the findings indicate that STUB1 is decreased in ACTH-secreting corticotroph adenomas and is negatively correlated with POMC expression and TPIT protein." (PMID 40859326, 2025). "Despite the extensive research on STUB1's functions in various biological processes and its emerging role in cancer biology, its specific involvement and potential mechanisms in corticotroph adenomas remain to be elucidated." (PMID 40859326, 2025). "Clinical investigations revealed that STUB1 expression is significantly lower in ACTH-secreting corticotroph adenomas than in silent corticotroph adenomas (SCAs)." (PMID 40859326, 2025). "Furthermore, immunohistochemistry (IHC) showed that nuclear-localized STUB1 was downregulated in ACTH-secreting corticotroph adenomas, accompanied by increased levels of TPIT, POMC, and ACTH compared to SCAs." (PMID 40859326, 2025). "Compared to SCAs, STUB1 was downregulated in ACTH-secreting corticotroph adenomas." (PMID 40859326, 2025). "Additionally, STUB1 was decreased in ACTH-secreting corticotroph adenoma compared to SCAs and negatively correlated with TPIT protein, as well as expression of POMC." (PMID 40859326, 2025). "Additionally, STUB1 was decreased in ACTH-secreting corticotroph adenoma compared to SCAs." (PMID 40859326, 2025).
developmental delay (1 paper, 2025). "Additionally, biallelic STUB1 variants have been reported in only four patients with neurodevelopmental disorders characterized by global developmental delay (GDD) and variable intellectual disability (ID)." (PMID 40542581, 2025).
hereditary ataxia (1 paper, 2014). An instance of an atactic disorder that is caused by an inherited genomic modification in an individual. "The patient's fibroblasts with a new form of hereditary ataxia, related to STUB1 gene (CHIP) mutations, and three age and sex-matched controls were treated with epoxomicin and trehalose." (PMID 25259530, 2014).
hyperlipidemia (1 paper, 2025). "In addition, we validated the reliability of HSP90AB1, HSPA5, and STUB1 as diagnostic genes for nephrolithiasis and hyperlipidemia through external validation." (PMID 40245021, 2025). "Ultimately, the best common diagnostic biomarkers for nephrolithiasis and hyperlipidemia were identified as 3 diagnostic genes (HSP90AB1, HSPA5 and STUB1)." (PMID 40245021, 2025). "The same ROC analysis was performed for the hyperlipidemia group, with HSP90AB1 (AUC=0.777), HSPA5 (AUC=0.838), and STUB1 (AUC=0.877) also showing robust predictive performance." (PMID 40245021, 2025).
influenza infection (1 paper, 2016). "TRIM32 and STUB1 are genes known to limit influenza infection." (PMID 27375580, 2016). "DBALIS found that overexpression of TRIM32, STUB1 and FKBP8 reduced influenza infection activity from two to four fold, indicating their role in viral restriction." (PMID 27375580, 2016).
nephrolithiasis (1 paper, 2025). The presence of a calculus in the pelvis of the kidney; this is most often composed of mineral salts and proteins. "Based on existing reports, we hypothesize that STUB1 may promote kidney stone formation by increasing tubular reabsorption, urinary osmolality, and the accumulation of oxalate and calcium ions in the kidney." (PMID 40245021, 2025). "Additionally, STUB1 can indirectly influence kidney stone formation by influencing affecting aquaporin 2 (AQP2), which regulates urine volume and osmolality." (PMID 40245021, 2025). "For nephrolithiasis biomarkers, the three pivotal genes, HSP90AB1 (AUC=0.857), HSPA5 (AUC=0.845), and STUB1 (AUC=0.872), showed strong predictive performance." (PMID 40245021, 2025).
urinary system diseases (1 paper, 2025). "We and others previously revealed that STUB1 play a vital role in urinary system diseases." (PMID 40651940, 2025).